MDH2 (malate dehydrogenase 2)
Diseases named in the same sentence as MDH2 in open-access papers (continued):
Sharing a sentence is not in itself a finding about the gene and the disease.
breast cancer (continued). "Through meticulous transcriptomic and metabolomic analyses, we have uncovered that alterations in MDH2 expression elicit profound changes in the transcriptomic landscape and metabolic profile of breast cancer cells." (PMID 41179294, 2025). "Using the HPA database, we also assessed MDH2 mRNA levels in 29 distinct tumor cell lines and found that MDH2 was highly expressed in all of these cell lines, with particularly high levels in breast cancer." (PMID 41179294, 2025). "To evaluate the role of MDH2 in breast cancer tumorigenesis in vivo, we subcutaneously implanted MDH2-OE or vector-infected MDA-MB-231 cells into nude mice." (PMID 41179294, 2025). "To explore how MDH2 expression modifies the metabolic profiles of breast cancer cells, we extracted polar metabolites from vector control and MDH2-OE MDA-MB-231 cell samples and performed untargeted LC-MS metabolomics analysis, as outlined in the flowchart." (PMID 41179294, 2025). "To elucidate the role of MDH2 in metastatic breast cancer cells, we performed MDH2 depletion in the highly metastatic MDA-MB-231 breast cancer cell line." (PMID 41179294, 2025). "Intriguingly, MDH2 transcript levels in breast cancer patients were strongly correlated with various clinicopathological features, including breast cancer subtype, pathological T stage, HER2 status, ER status, PR status, race, and histological type." (PMID 41179294, 2025). "To explore the role of MDH2 in breast cancer, we used two distinct small interfering RNAs (si-MDH2-1 and si-MDH2-2) to transiently suppress MDH2 expression in MDA-MB-231 and MDA-MB-453 cells." (PMID 41179294, 2025). "To elucidate the prognostic significance of MDH2 in breast cancer, we stratified patients into high and low MDH2 expression groups and assessed their OS and DSS." (PMID 41179294, 2025). "To investigate the impact of MDH2 on breast cancer tumor proliferation in vivo, we engineered MDH2-OE MDA-MB-231 cells." (PMID 41179294, 2025). "Our findings highlight the role of MDH2 in breast cancer metabolism and suggest it as a promising target for cancer therapies targeting metabolism and tumor growth." (PMID 41179294, 2025). "Our in vitro studies demonstrated that suppressing MDH2 expression in breast cancer cells significantly induced apoptosis, inhibited cell proliferation, altered cell cycle distribution, and induced G2 phase arrest." (PMID 41179294, 2025). "To further elucidate how MDH2 promotes breast cancer progression from a metabolic standpoint, we integrated metabolomic and transcriptomic data to analyze the changes in relevant molecular profiles of MDH2 when regulating progression." (PMID 41179294, 2025). "In summary, our comprehensive investigation has firmly established MDH2 as a novel oncogene in breast cancer." (PMID 41179294, 2025). "Specifically, MDH2 expression was significantly elevated in patients with advanced breast cancer compared to those with early-stage disease, and it was also higher in patients with ER (-) and PR (-) status." (PMID 41179294, 2025). "Transcriptomic profiling revealed MDH2 had modified the gene expression profile of breast cancer cells, affecting several metastasis-related genes." (PMID 41179294, 2025). "MDH2 expression was highest in the basal-like breast cancer subtype, followed by the Luminal-B and Luminal-A subtypes." (PMID 41179294, 2025). "To validate the oncogenic role of MDH2 in breast cancer, we conducted a series of in vitro and in vivo experiments." (PMID 41179294, 2025). "Our results revealed that MDH2 is abnormally overexpressed at both the mRNA and protein levels in breast cancer tissue samples." (PMID 41179294, 2025). "Our analysis shows that the levels of multiple immune cell infiltration are substantially negatively correlated with MDH2 expression, and these levels of significantly impact the survival outcomes of breast cancer patients with high or low MDH2 expression." (PMID 41179294, 2025).
breast cancer (continued). "Conversely, in vivo experiments have demonstrated that overexpression of MDH2 robustly drives the growth of breast cancer xenograft tumors." (PMID 41179294, 2025). "MDH2 expression levels in breast malignancies with varying receptor status have implications for treating breast cancer." (PMID 41179294, 2025). "In vitro, MDH2 depletion suppressed breast cancer cell proliferation and migration, reversed EMT, and markedly reduced glucose consumption and ATP production." (PMID 41179294, 2025). "Collectively, these findings suggest that MDH2 overexpression enhances the growth and proliferation of breast cancer tumors." (PMID 41179294, 2025). "Among breast cancers of different histological types, infiltrating ductal carcinoma had higher MDH2 expression than infiltrating lobular carcinoma." (PMID 41179294, 2025). "This approach enabled us to investigate the molecular mechanisms of MDH2 in breast cancer progression on a genome-wide scale with high sensitivity." (PMID 41179294, 2025). "Our analysis revealed that modulating MDH2 expression significantly impacts the genomic landscape of breast cancer cells." (PMID 41179294, 2025). "Collectively, these results indicate that MDH2 suppression inhibits the proliferation of breast cancer cells." (PMID 41179294, 2025). "We combined in vitro cell-based assays with mouse xenograft models to systematically dissect how MDH2 governs breast cancer growth." (PMID 41179294, 2025). "Collectively, these findings led us to hypothesize that MDH2 may exert a pro-oncogenic function in breast cancer and could serve as a biomarker for diagnosis, treatment, and prognosis in breast cancer patients." (PMID 41179294, 2025). "Consequently, investigating the relationship between MDH2 expression and immune infiltration in breast cancer is imperative." (PMID 41179294, 2025). "Our experimental findings suggest that MDH2 is a potential drug target for breast cancer treatment." (PMID 41179294, 2025). "Collectively, these studies, including our own, suggest that MDH2 functions as an oncogene in breast cancer and may represent a druggable target for its treatment." (PMID 41179294, 2025). "Therefore, identifying the metabolites involved in MDH2’s regulation of breast cancer development is crucial." (PMID 41179294, 2025). "In addition to its role in tumor growth, our research also uncovered that MDH2 regulates cell motility, particularly cell migration, which is a critical step in breast cancer progression." (PMID 41179294, 2025). "However, the function of MDH2 in breast cancer remains largely unexplored, necessitating further investigation." (PMID 41179294, 2025). "Notably, MDH2 expression promotes adenosine production and inhibits linoleic acid synthesis in breast cancer." (PMID 41179294, 2025). "In the present study, we will focus on elucidating the potential role of MDH2 in breast-cancer initiation and progression and on evaluating its feasibility as a novel therapeutic target, thereby providing a theoretical foundation for subsequent mechanistic studies and precision-treatment strategies." (PMID 41179294, 2025). "While MDH2 mutations have not previously been observed in breast cancer cases, decreased expression of MDH2 has been observed in triple-negative breast cancer cases compared to HER2-positive breast cancer cases, supporting a role of MDH2 in breast cancer." (PMID 38136396, 2023). "Therefore, we hypothesize that MDH2 may promote breast cancer development by activating these pathways." (PMID 41179294, 2025). "Only three variants were observed not only in the affected cousin pair, but also in the other recurrent breast cancer cases sequenced in the same pedigree (in genes TENM2, CCDC136, and MDH2)." (PMID 38136396, 2023). "MDH2, a key enzyme in the TCA, likely impacts glycolysis in breast cancer cells." (PMID 41179294, 2025).
breast cancer (continued). "Given the putative pro-cancer function of MDH2, developing drugs that modulate the activity may offer a novel therapeutic strategy for breast cancer." (PMID 41179294, 2025).
endometrial carcinoma (4 papers, 2022 to 2025). A malignant tumor arising from the epithelium that lines the cavity of the uterine body. "As a metabolism-related enzyme, MDH2 is overexpressed in endometrial carcinoma tissues and correlated with its grade." (PMID 36968582, 2023). "It has been published that MDH2 is an estrogen-regulated gene and that MDH2 promotes proliferation, migration, and invasion of endometrial cancer cells while suppressing their apoptosis." (PMID 38136396, 2023). "MDH2 was also overexpressed in endometrial carcinoma tissues and was related to the grade of the cancer." (PMID 36159820, 2022).
epilepsy (4 papers, 2020 to 2023). A brain disorder characterized by episodes of abnormally increased neuronal discharge resulting in transient episodes of sensory or motor neurological dysfunction, or psychic dysfunction. "In AGC1- and MDH2-deficiency, the most striking and most immediate effect was the one against seizures in these severe epilepsies." (PMID 36079864, 2022). "Human disease has been linked to biallelic pathogenic variants in MDH1, MDH2, GOT2 and SLC25A12 sharing a clinical overlapping neurological phenotype with epilepsy as dominating feature." (PMID 36079864, 2022). "Our results showed a higher amount of MDH2 in patients with epilepsy compared with those suffering from PNES." (PMID 33244522, 2020).
hepatocellular carcinoma (4 papers, 2017 to 2024). A malignant tumor that arises from hepatocytes. "MDH2 deficiency inhibits the growth of hepatocellular carcinoma (HCC) cells and enhances their sensitivity to ferroptosis induced by RAS-selective lethal 3 (RSL3), a compound known to cause ferroptosis." (PMID 39519171, 2024). "In addition, an increase in isoform 2 of malate dehydrogenase was observed in mtGR-expressing tumors in line with previous observations, demonstrating increased malate dehydrogenase-2 in hepatocellular carcinoma and proposing MDH-2 as a new cancer biomarker." (PMID 36835152, 2023). "ALDH, MDH2 and CMPK exhibited increased expression in human hepatoma 7.5 cells (HUH7.5) infected with Hepatitis C virus (HCV) and FAH was decreased in HCV-associated carcinoma tissue." (PMID 28086865, 2017).
sarcopenia (4 papers, 2024 to 2026). Progressive decline in muscle mass due to aging which results in decreased functional capacity of muscles. "Recent studies have revealed that the downregulation of MDH2 may contribute to the promotion of muscle ferroptosis in sarcopenia." (PMID 39519171, 2024). "Recent investigations have suggested that reduced MDH2 expression in sarcopenia may promote muscle ferroptosis." (PMID 39519171, 2024). "From a clinical perspective, the potential of ENSA, FAM43A, MDH2, NUBP1, SAMM50, and TM2D1 as biomarkers is promising, as they may be measurable in peripheral blood or muscle biopsy specimens to support early screening and individualized diagnosis of AS patients at risk of sarcopenia." (PMID 41204493, 2025).
Duchenne muscular dystrophy (3 papers, 2020 to 2024). Duchenne muscular dystrophy (DMD) is a neuromuscular disease characterized by rapidly progressive muscle weakness and wasting due to degeneration of skeletal, smooth and cardiac muscle. "Another example is MDH2 (malate dehydrogenase 2), a mitochondrial enzyme identified as a promising prognostic biomarker for Duchenne muscular dystrophy." (PMID 39595553, 2024). "Serum levels of MDH2 significantly decrease with age in Duchenne muscular dystrophy patients, correlating with disease progression." (PMID 39595553, 2024). "A deficiency of malate dehydrogenase is linked to muscular system pathologies as reductions in both isoforms (MDH1 and MDH2) of malate dehydrogenase have been demonstrated in Duchenne muscular dystrophy." (PMID 39519852, 2024).
glioma (3 papers, 2017 to 2023). A benign or malignant brain and spinal cord tumor that arises from glial cells (astrocytes, oligodendrocytes, ependymal cells). "MDHDH reduced the protein level of MDH2 in glioma stem cells, and down-regulation of PSMA1 rescued the protein level of MDH2." (PMID 36527092, 2022). "In the present study, we found that the downregulated lncRNA MDHDH interacted with MDH2 and was negatively correlated with the WHO grade classification of gliomas." (PMID 36527092, 2022). "We also investigated the alteration of NAD+ and the NAD+/NADH ratio in glioma cells, and further confirmed that the changes in metabolic status were induced by MDHDH-related MDH2 degradation." (PMID 36527092, 2022). "The lncRNA MDHDH is characterized by a full length of 749 nt and is located at chromosome X. When the expression level of MDHDH was artificially upregulated in glioma cell lines, we observed significant remodeling of NAD+ metabolism as well as enhanced MDH2 degradation." (PMID 36527092, 2022). "The phenotypic reversion caused by knockdown of PSMA1 may be associated with the blocked degradation and increased protein levels of MDH2, suggesting that UPS may also be involved in the regulatory aspects of metabolic function in glioma cells." (PMID 36527092, 2022). "In addition, the immunofluorescence results indicate that upregulation of MDHDH promoted the colocalization of MDH2 and PSMA1 in glioma cells, further suggesting that MDHDH plays a role in the interaction between MDH2 and PSMA1." (PMID 36527092, 2022). "In contrast, expression levels of enzymes involved in downstream metabolism of isocitrate, including IDH1, IDH2 and IDH3A, α-KGDH, succinate dehydrogenase (SDHB), fumarate hydratase (FH) and malate dehydrogenase (MDH2), were remarkably lower in IDH1MUT glioma versus IDH1WT glioma." (PMID 28467784, 2017). "However, studies on the precise mechanisms of MDH2 posttranslational regulation and its potential effects on NAD+ metabolism are still lacking, especially in glioma." (PMID 36527092, 2022).
Hyperglycemia (3 papers, 2022 to 2024). An increased concentration of glucose in the blood. "In contrast to other metabolic enzymes, such as GAPDH, whose activity is SUMOylation-dependant, the increased activity of MDH2 following SUMOylation is likely to maintain ETS functionality and energy supply and thereby help to overcome cellular stress and damage caused by hyperglycaemia." (PMID 37947589, 2023).
ischemia (3 papers, 2019 to 2023). A hypoperfusion of the BLOOD through an organ or tissue caused by a PATHOLOGIC CONSTRICTION or obstruction of its BLOOD VESSELS, or an absence of BLOOD CIRCULATION. "Previous studies, reported in the literature, reveal that ischemia reduces the activity of MDH2 in the heart." (PMID 31109015, 2019).
myocardial ischemia (3 papers, 2025). A disorder of cardiac function caused by insufficient blood flow to the muscle tissue of the heart. "Dexmedetomidine also improves myocardial ischemia–reperfusion injury by inhibiting MDH2 lactation through regulating metabolic reprogramming." (PMID 41195185, 2025). "Myocardial ischemia–reperfusion injury features OXPHOS suppression with compensatory glycolysis, whereby the K241 lactylation of malate dehydrogenase 2 (MDH2), a key enzyme of the TCA cycle, promotes ferroptosis and mitochondrial dysfunction." (PMID 40806283, 2025).
pancreatic cancer (3 papers, 2020 to 2025). "In this study, we evaluated the efficacy of metformin, an inhibitor of oxidative phosphorylation, in combination with LW6, which impairs malate dehydrogenase 2 activities, in treating pancreatic cancer cells." (PMID 31897243, 2020).
uterine cancer (3 papers, 2015 to 2021). Primary or metastatic malignant neoplasm involving the uterine corpus and/or the cervix. "Thus, MDH2 is potentially to be a mitochondrial marker for the diagnosis of doxorubicin-associated drug resistance in uterine cancer." (PMID 25639359, 2015). "Further investigation demonstrated that the level of mitochondria-located mitochondrial protein MDH2 was significantly increased in resistant line MES-SA/Dx-8 μM rather than in MES-SA or in MES-SA/Dx-2 μM implying MDH2 is over-expressed in highly resistant uterine cancer cells." (PMID 25639359, 2015).
Alzheimer disease (2 papers, 2024 to 2025). A progressive, neurodegenerative disease characterized by loss of function and death of nerve cells in several areas of the brain leading to loss of cognitive function such as memory and language. "Mdh2 is the final enzyme in the mitochondrial tricarboxylic acid cycle and its activity is associated with increased oxidative stress in the brain of Alzheimer disease." (PMID 39250516, 2024).
asthma (2 papers, 2012 to 2024). "Some of these genes were altered sex specifically in the placenta of asthmatic women, including GAPDH which was only altered in males, while MDH2, COMT, and CPOX were decreased in female placentae of pregnancies complicated by asthma." (PMID 22830026, 2012). "The presence and absence of inhaled glucocorticoid use for asthma treatment during pregnancy also influenced mitochondrial gene expression, with MDH2, COMT, and CPOX gene expression being increased in placentae of females whose mothers' used these inhaled steroids during pregnancy." (PMID 22830026, 2012).
colon cancer (2 papers, 2015 to 2022). "Additionally, our identification of RNF8-interacting ENO1, LDH1, PKM, PYCR, and MDH2 might provide other mechanisms underlying RNF8-regulated colon cancer progression." (PMID 35831895, 2022).
colorectal cancer (2 papers, 2016 to 2024). A primary or metastatic malignant neoplasm that affects the colon or rectum. "Inhibition of MDH2 reduces NADH levels and cellular ATP production in colorectal cancer cells, which in turn inactivates ACC and mTOR signaling pathways." (PMID 39403185, 2024).
insulinoma (2 papers, 2014 to 2015). "Gluconeogenic enzymes FBPase and MDH2 have also been identified in exosomes purified from the mouse insulinoma NIT-1 cells." (PMID 25192542, 2014).
myocardial infarction (2 papers, 2025). Gross necrosis of the myocardium, as a result of interruption of the blood supply to the area, as in coronary thrombosis. "The delayed plasma detection of MDH2 highlights its temporal regulation in myocardial infarction." (PMID 41399465, 2025).
non-small cell lung carcinoma (2 papers, 2023 to 2024). A group of at least three distinct histological types of lung cancer, including non-small cell squamous cell carcinoma, adenocarcinoma, and large cell carcinoma. "The levels of MDH1 and MDH2 enzymes in the cytoplasm and mitochondria of non-small-cell lung cancer (NSCLC) cells have been shown to be elevated compared with normal cells, and MDH1 enzyme activity was significantly higher than that of MDH2." (PMID 37151882, 2023).
pancreatic adenocarcinoma (2 papers, 2024). "Notably, the MDH2 expression level in SW1990, a cell subtype established from a spleen metastasis of pancreatic adenocarcinoma, was 11.6% and 20.1% lower than that in BxPC3 and Panc1 cells." (PMID 38483955, 2024).
Stroke (2 papers, 2024 to 2025). Sudden impairment of blood flow to a part of the brain due to occlusion or rupture of an artery to the brain. "Our group has shown that lncRNA U90926 expression is elevated in microglia after stroke and promotes neutrophil infiltration by competitively binding to malate dehydrogenase 2 (MDH2), which stabilizes CXCL2 mRNA." (PMID 41367136, 2025).
brain glioma (1 paper, 2022). A malignant glioma that involves the brain. "A prognostic model based on nine signature glycolytic genes, including MDH2, can accurately predict the prognosis of brain glioma patients." (PMID 36159820, 2022).
brain infarct (1 paper, 2020). "The downregulated MDH2 may be responsible for the failure of energy metabolism in brain infarct regions through the metabolic in-coordination between cytosol and mitochondria." (PMID 32174813, 2020).